XAGE5 (X antigen family member 5)
Synonyms: XAGE-5; CT12.5; GAGED5
Tractability: No criterion of Open Targets' tractability assessment is met for any kind of drug.
Gene: Protein-coding gene on chromosome X (52,811,287 to 52,818,301, forward strand). Ensembl gene ENSG00000171405.
Subcellular location (Human Protein Atlas): Nucleoplasm; Vesicles
Homologues: Orthologues: chimpanzee XAGE5 (94% identical). Paralogues in human: XAGE3 (75% identical), XAGE2 (69% identical), PAGE3 (49% identical), GAGE10 (48% identical), GAGE1 (44% identical), GAGE12H (44% identical), GAGE13 (44% identical), GAGE2A (44% identical), GAGE12C (43% identical), GAGE12D (43% identical), GAGE12E (43% identical), GAGE12F (43% identical), and 10 more.
Diseases named in the same sentence as XAGE5 in open-access papers:
XAGE5 is named in the same sentence as 3 diseases in open-access papers, as found by Europe PMC text mining. Sharing a sentence is not in itself a finding about the gene and the disease.
XAGE5 shares sentences with these, for which no sentence is quoted: cancer (2 papers); melanoma (1); tumor (1).